PVR (PVR cell adhesion molecule)
Diseases named in the same sentence as PVR in open-access papers (continued):
Sharing a sentence is not in itself a finding about the gene and the disease.
glioblastoma (34 papers, 2004 to 2025). The most malignant astrocytic tumor (WHO grade IV). "The poliovirus naturally binds to CD155, also known as poliovirus receptor (PVR), which is expressed at high levels in many tumor cells, including glioblastoma cells." (PMID 38396720, 2024). "Blocking CD155/PVR/Necl-5 with anti-CD155/PVR/Necl-5 antibodies and the knockdown of CD155/PVR/Necl-5 by RNAi resulted in decreased migration of glioblastoma cells." (PMID 23833639, 2013). "The knockdown of CD155/PVR/Necl-5 in glioblastoma cells also decreased the matrix metalloproteinase-2 (MMP-2) expression and activity and resulted in markedly decreased cell invasion." (PMID 23833639, 2013). "SCARB2-expressing hepatocellular carcinoma cells or ICAM-1-positive triple-negative breast cancer cells could be targeted by EV71 or Coxsackievirus A, while PVR-expressing glioblastomas could be targeted by polioviruses." (PMID 39335111, 2024). "It has been reported that glioblastoma (GBM) CSCs are vulnerable to IL-2/IL-15-activated NK cells due to their expression of cytotoxicity receptors and ligands (i.e., PVR and Nectin-2) and the reduction of MHC-I molecules on their surface." (PMID 33530455, 2021). "Nectin-2, like PVR, binds to DNAM-1, a NK cell co-activating receptor involved in NK lysis of human glioblastoma." (PMID 23762498, 2013).
hepatocellular carcinoma (34 papers, 2017 to 2026). A malignant tumor that arises from hepatocytes. "High PVR expression correlates with poor prognosis and increased invasiveness, as observed in hepatocellular carcinoma and lung squamous cell carcinoma, where elevated PVR levels are associated with decreased overall and recurrence-free survival rates." (PMID 40621458, 2025). "For this purpose, we co-cultured isolated pbNK cells from healthy individuals with the human hepatoma cell line Huh7, which stably expresses PVR." (PMID 36845105, 2023). "Immunohistochemistry showed PVR protein was mainly distributed in cytoplasm and membrane, and was moderately expressed in hepatocellular carcinoma and urothelial carcinoma compared to corresponding normal tissues respectively." (PMID 34150627, 2021). "Taken together, these data show that CD56bright pbNK cells altered their phenotypes towards CD56bright ihNK cells when cultured together with PVR-expressing human hepatoma cells, by downregulating activating and simultaneously upregulating inhibitory NK cell receptors that bind to PVR." (PMID 36845105, 2023). "Overexpression of PVR has been reported in many cancers including melanoma, lung adenocarcinoma, ovarian cancer, myeloid leukemia, neuroblastoma, pancreatic cancer, colorectal cancer, hepatocellular carcinoma, and bladder cancer." (PMID 34150627, 2021). "Importantly, co-culture with PVR-expressing human hepatoma cells or primary hepatocyte organoids enhanced TIGIT expression and reduced DNAM-1 expression on CD56bright pbNK cells, suggesting a potential influence of the liver environment on the phenotype and function of ihNK cells." (PMID 36845105, 2023). "Furthermore, PVR is overexpressed in several types of cancers, including serous ovarian cancer, colorectal carcinoma, hepatocellular carcinoma, lung adenocarcinoma, esophageal small cell carcinoma, and cholangiocarcinoma, and highly expressed in bone marrow cells in multiple myeloma (MM)." (PMID 35625835, 2022). "However, the correlation between PVR expression and prognosis as well as immune infiltration in hepatocellular carcinoma (HCC) remains unclear." (PMID 36552960, 2022). "We continued to investigate the therapeutic potential of blocking novel immune checkpoint molecules PVR and PVRL2 for hepatocellular carcinoma through in vitro immune cell mediated cytotoxicity assays." (PMID 37383234, 2023). "The activation of Unfolded Protein Response (UPR) resulted in down-regulation of PVR surface expression by protein degradation in hepatocellular carcinoma, while upon CMV infection an immature form of PVR is retained in ER by the viral protein UL141." (PMID 28874810, 2017).
colorectal cancer (31 papers, 2013 to 2026). A primary or metastatic malignant neoplasm that affects the colon or rectum. "TIGIT and its ligand CD155 (PVR) are emerging immune checkpoints in colorectal cancer (CRC), but their associations with mutational subtypes and the tumor immune milieu remain unclear." (PMID 41596586, 2026). "The elevated expression of PVR facilitates the immune escape of tumor cells including melanoma, head and neck squamous cell carcinoma, and colorectal cancers." (PMID 34068552, 2021). "Here, we confirmed the overexpression of PVR on a broad spectrum of cancers, especially in colorectal cancers." (PMID 32894141, 2020). "Meanwhile, PVR expression was also analyzed in Oncomine, which PVR expressed higher in colorectal cancers, esophagus cancers, gastric cancers, renal cancers and leukemia than corresponding normal tissues." (PMID 32894141, 2020). "The further analysis focused on colorectal cancer observed that PVR expressed higher in colorectal cancer tissues than normal tissues to both non-paired samples of GSE37182 and 24 paired samples of GSE10972." (PMID 32894141, 2020). "Here, we found that PVR also overexpressed in many tumors inkling colorectal cancers, and the expression level increased during the tumor development." (PMID 32894141, 2020). "It has been reported that PVR was highly expressed in a variety of tumors, including colorectal cancer, breast cancer, small cell lung cancer, head and neck squamous cell carcinoma, melanoma and gastric cancer." (PMID 32894141, 2020). "Besides, the flow cytometry results also showed that PVR expressed on both human and murine colorectal cancer cell lines." (PMID 32894141, 2020). "CD155, also called poliovirus receptor (PVR), is a protein that is significantly overexpressed in solid human cancers such as gastric cancer, esophageal cancer, and colorectal cancer, but with limited or no expression in normal tissues." (PMID 41394877, 2025).
lung adenocarcinoma (30 papers, 2012 to 2026). A carcinoma that arises from the lung and is characterized by the presence of malignant glandular epithelial cells. "It has also been reported that miRNAs regulate PVR expression in lung adenocarcinomas." (PMID 39156900, 2024). "Treatment of lung adenocarcinoma cells with the natural product rediocide-A could decrease the expression of CD155/PVR and increase NK cell-mediated anti-tumor cytotoxicity." (PMID 34374809, 2022). "Only one report has shown that the expression of PVR, PVRL2, TIGIT, PD-1, and PD-L1 in lung adenocarcinoma is heterogeneous within and between tumors and varies according to tumor growth patterns, so future reports are expected." (PMID 39156900, 2024). "We performed immunohistochemical staining of 84 tumor segments from 22 resected tumor samples to evaluate the expression of PD-L1, PD-1, Nectin-2, PVR, and TIGIT in distinct growth patterns of lung adenocarcinoma." (PMID 34102454, 2021). "PVR expressed in head and neck cancer (HNSC), lung adenocarcinoma (LUAD) and stomach cancer (STAD), which was consistent with the previous study." (PMID 32894141, 2020). "In several tumor entities, including lung adenocarcinoma, the expression of this regulatory receptor was found to be increased on TILs, giving tumor cells an additional option to escape the immune system in suppressing the functions of the TILs, when TIGIT binds one of its ligands Nectin-2 or PVR." (PMID 34102454, 2021).
multiple myeloma (29 papers, 2015 to 2026). "For instance, metformin treatment enhances the expression of NKG2D ligands (RAE-1 and MULT-1) and DNAM-1 ligands (PVR/CD155) on multiple myeloma (MM) cells, thereby increasing NK cell recognition and cytotoxicity against tumor cells." (PMID 40703657, 2025). "These markers highlight the potential for using PVR expression, serum amylase, and UIGFBp7/creatinine as independent predictors for survival in multiple myeloma." (PMID 40369504, 2025). "Significantly elevated PVR expression and serum levels in cases (p=0.003 and p<0.001, respectively) reinforce their potential as reliable biomarkers for multiple myeloma." (PMID 40369504, 2025). "Collectively, these findings highlight the multifaceted role of PVR as a biomarker, linking it to systemic, metabolic, and hematological abnormalities in multiple myeloma." (PMID 40369504, 2025). "The correlations between PVR gene expression, serum levels, serum amylase, and urinary biomarkers with clinical characteristics in multiple myeloma patients were analyzed." (PMID 40369504, 2025). "Myeloma cells with NLRC5 mutations and overexpression of selected genes including TNFRSF10D, NCR3LG1, ULBP1, PVR, and PCGF5 were sensitive to NK cells." (PMID 38410372, 2024). "Myeloma cells with TRAF3 and WHSC1 mutations and overexpression of TNFRSF10D, NCR3LG1, ULBP1, PVR, and PCGF5 were tolerance to NK cells." (PMID 38410372, 2024). "Here, we focused on the SUMO pathway and demonstrated that the ligand of DNAM1 activating receptor, PVR, undergoes SUMOylation in multiple myeloma." (PMID 28874810, 2017). "In this study, we investigated the effect of different nitric oxide (NO) donors on the expression of the DNAM-1 ligand Poliovirus Receptor/CD155 (PVR/CD155) in multiple myeloma (MM) cells." (PMID 25609078, 2015). "The anti-leukemic action of NK cells would also be strengthened by the ability of SUMOylation inhibition to induce the expression of NK-activating ligands at the surface of cancer cells, as we demonstrated for ICAM-1 on AML cells and as it was shown for PVR on Multiple Myeloma cells." (PMID 40661051, 2026). "Thus, PVR overexpression on myeloma cells impairs anti-tumor immune responses, promoting immune escape and disease progression." (PMID 40369504, 2025). "Our findings imply these cells may exhibit enhanced NO production, which could subsequently upregulate PVR expression via feedback mechanisms analogous to those documented in myeloma models." (PMID 40977889, 2025). "To investigate the association between PVR expression, serum amylase, IGFBP-7, and TIMP-2 with the survival outcomes of multiple myeloma (MM) patients, we analyzed the overall survival (OS) and progression-free survival (PFS) in relation to PVR expression status." (PMID 40369504, 2025). "Additionally, other authors observed that IMiDs may enhance the susceptibility of myeloma cells to NK cell-mediated recognition and killing by increasing the expression of MICA and PVR (the ligand for DNAM-1 receptor) in myeloma cells." (PMID 33802806, 2021). "In multiple myeloma cells, CBIs raise the levels of the NK-activating ligands MICA and PVR through cereblon-dependent degradation of IKZF-1/3 and IRF4." (PMID 33411730, 2021). "We observed that PVR expression was selectively reduced both at level of mRNA and protein upon blockade of CXCR1/2 receptors on myeloma cells as well as by depletion of IL-8 via shRNA in BMSCs." (PMID 32069911, 2020). "The"Poliovirus receptor"(PVR), also known as CD155, is a crucial glycoprotein in the nectin-like protein family, playing a very important role in immune responses and diseases such as multiple myeloma." (PMID 40369504, 2025). "Chemotherapeutic drugs, including doxorubicin, melphalan and bortezomib, upregulate both the DNAX accessory molecule-1 (DNAM-1; CD226) ligand PVR (poliovirus receptor; CD155) and NKG2D ligands (MICA and MICB) on multiple myeloma cells presenting a senescent phenotype." (PMID 32164335, 2020).
multiple myeloma (continued). "The present study provides evidence that regulation of the PVR/CD155 DNAM-1 ligand expression by nitric oxide may represent an additional immune-mediated mechanism and supports the anti-myeloma activity of nitric oxide donors." (PMID 25609078, 2015). "Poliovirus receptor (PVR, CD155) is upregulated during tumor progression, and PVR expression is associated with poor prognosis in cancer patients; however, prognostic implications for PVR in multiple myeloma (MM) have not been investigated." (PMID 35625835, 2022).
lung carcinoma (27 papers, 2013 to 2025). "In the PVR-positive A427 lung cancer model, studies have demonstrated that therapeutic strategies targeting KIR2DL5+TIGIT+ NK cells achieve significantly greater efficacy when employing KIR2DL5 blockade compared to TIGIT blockade." (PMID 40463500, 2025). "This study was designed to provide a more detailed understanding of TIGIT function on activated human NK cells derived from healthy donors prior to, and after, exposure to PVR-expressing lung cancer spheroids." (PMID 37345049, 2023). "TIGIT blockade increased PM21-NK cell cytotoxicity against 3D lung cancer spheroids and prevented PVR-mediated dysfunction after exposure to tumor spheroids." (PMID 37345049, 2023). "We transduced primary NK cells with KIR2DL5 and cocultured with human lung cancer A427 and leukemic Jurkat tumor cells that expressed endogenous PVR." (PMID 36377656, 2022). "Targeting T-Cell Immunoreceptor with Ig and ITIM domain-poliovirus receptor (PVR) pathway is a potential therapeutic strategy in lung cancer." (PMID 33879814, 2021).
gastric cancer (22 papers, 2016 to 2026). A primary or metastatic malignant neoplasm involving the stomach. "The RT-PCR fold-change data from this study provide an overview of B7-H3 (CD276) and CD155 (PVR) gene expression in gastric cancer." (PMID 41225987, 2025). "Consistent with previous reports in the public database The Cancer Genome Atlas (TCGA), CD47 and PVR expressed at high levels in Esophageal Cancer (ESCA), Colon Cancer (COAD), Head and Neck Cancer (HNSC), and Stomach Cancer (STAD) analyzed by the online tool TIMER." (PMID 34068552, 2021).
colon carcinoma (21 papers, 2004 to 2025). "Recent findings highlight its therapeutic potential, especially in colon cancer, where acetate therapy has been shown to inhibit the expression of the immunological checkpoint ligand PVR/CD155, thereby enhancing the effector responses of CD8+ T cells and potentially boosting anti-tumor immunity." (PMID 39351241, 2024). "PVR knockdown inhibited colon cancer cell migration and invasion by reducing FAK, Src, and MMP−2." (PMID 36552960, 2022).
viral infection (19 papers, 2011 to 2025). "The PVR/ERK pathway has been documented to play a role in enterocyte host defense against viral infections." (PMID 39975242, 2025). "Expression levels of the inhibitory receptor, T cell immunoglobulin and ITIM domain (TIGIT), the co-stimulatory receptor CD226 and their ligand PVR are altered in viral infections and cancer." (PMID 28084312, 2017). "Guanidine treatment caused significant reductions in total viral yield in Tnfr1+/+PVR+/+ mice after 4 days of viral infection and in Tnfr1−/−PVR+/+ mice after 5 days of infection." (PMID 25365453, 2014). "With a similar virus infection setup as described for the PVR-/-;PVRL2-/- cells, we synchronized virus attachment to the HST2ST1 KO and control cells on ice for an hour, treated them with the acid wash at 3h.p.i., then harvested the total viruses produced by these cells at 16h.p.i." (PMID 38400072, 2024). "Virus-infected cell recognition by NK cells is not pathogen-specific in the vast majority of cases, but rather depends on recognition of cell ligands to activating receptors that are induced by virus infection (e.g. PVR, Nectin-2, MIC-a, MIC-b, ULBPs, B7-H6 etc)." (PMID 33861802, 2021). "Following viral infection and in cancer, DNA damage can upregulate the expression of PVR." (PMID 33902006, 2021). "At later stages of infection, VZV downregulated various other types of cell surface receptors, including the oxytocin receptor (OXTR), GDNF family receptor alpha-1 (GFRA1) and the poliovirus receptor (PVR; CD155), suggesting a more broad effect of virus infection on cell surface receptors." (PMID 32547533, 2020). "Further demonstrating the specificity for LPS in enhancing poliovirus binding to PVR, incubation of poliovirus with LPS failed to promote viral infection on non-PVR expressing cells; and blocking PVR with a specific antibody prevented poliovirus infection irrespective of the presence of LPS." (PMID 31426458, 2019).
ovarian carcinoma (16 papers, 2013 to 2025). A malignant neoplasm originating from the surface ovarian epithelium. "In 2007, it was shown that PVR is expressed in ovarian cancer cells and enhances NK cell activity via the DNAM1 pathway." (PMID 39156900, 2024). "Recently, focal adhesion kinase (FAK) was reported to function in tumor immunosuppression of ovarian cancer via the PVR/TIGIT pathway." (PMID 39156900, 2024). "Thus, the epithelial origin of CAISMOV24 cells was confirmed by the expression of EpCAM and PVR, two molecules expressed by ovarian epithelial cells, which are frequently overexpressed in ovarian carcinomas." (PMID 29132324, 2017).
cervical carcinoma (12 papers, 2009 to 2025). A carcinoma arising from either the exocervical squamous epithelium or the endocervical glandular epithelium. "In vitro and in vivo, the silencing of PVR inhibited cervical cancer cell proliferation, cell viability, and induced cell-cycle arrest." (PMID 36552960, 2022). "In cervical cancer, PVR expression gradually increased with the degree of cervical lesions." (PMID 36552960, 2022). "For immunostimulator, SLC30A1 expression positively correlated with IL6R (Spearman: ρ = 0.204, P = 0.000345), TNFSF15 (Spearman: ρ = 0.355, P = 2.19e-10), NT5E (Spearman: ρ = 0.299, P = 1.16e-07), and PVR (Spearman: ρ = 0.236, P = 3.29e-05) in cervical carcinoma." (PMID 35154468, 2022). "We observed that CD274, CEACAM1, LGALS9, PVR and TNFRSF14 were significantly different (P < 0.05) between two groups, providing a novel insight into immunotherapy for cervical carcinoma patients." (PMID 34789197, 2021).
leukemia (12 papers, 2013 to 2025). A malignant (clonal) hematologic disorder, involving hematopoietic stem cells and characterized by the presence of primitive or atypical myeloid or lymphoid cells in the bone marrow and the blood. "Interestingly, all leukemia cell lines expressed ligands to PVR/Nectin family members (CD112 and CD155), except for HL-60 showing only the expression of CD155." (PMID 38967649, 2024). "Relevant receptors involved in anti-leukemia activity are NKp46, NKp30, and NKp44 (collectively called natural cytotoxicity receptors, NCR), whose surface-bound ligands are still not completely defined, NKG2D interacting with MICA/B and ULBPs, and DNAM-1 recognizing PVR (CD155) and Nectin-2 (CD112)." (PMID 32764469, 2020). "Furthermore, we could show that the majority of leukemia-initiating cells, defined as being CD34+/CD38−, expressed PVR and PVRL2 or at least one of the immune checkpoint ligands (mean expression value 77%, range 51–93%, n = 10)." (PMID 29855615, 2018). "To date, the role of GSK-3 in the regulation of activating ligands on leukemia cells remains unclear, given the results of a previous study that only used pharmacological agents for GSK-3 inhibition and only assessed the limited ligands (i.e., MICA/B and PVR/CD155) for NKG2D and DNAM-1." (PMID 33918810, 2021).